MTOR (mechanistic target of rapamycin kinase)
Diseases named in the same sentence as MTOR in open-access papers (continued):
Sharing a sentence is not in itself a finding about the gene and the disease.
cardiovascular diseases (125 papers, 2010 to 2025). "Inspired by these insights, researchers have increasingly linked mTOR with cardiovascular disease, progressively uncovering its critical role in the pathogenesis of heart disease and developing targeted therapeutic strategies aimed at mTOR." (PMID 40002810, 2025). "Recent studies have demonstrated that sustained mTOR signaling activation linked obesity with vascular senescence and cardiovascular diseases." (PMID 35111365, 2022). "It has been reported that cardiovascular disease was closely regulated through the signaling pathways of the mammalian target of rapamycin (mTOR) which was associated with endothelial cell survival and growth, as well as cardiomyocyte proliferation." (PMID 23547730, 2013). "Interestingly, high concentrations of branched chain amino acids, particularly leucine, have been linked to inflammation and cardiovascular disease because of their potency in activating mTOR in leukocytes." (PMID 35202654, 2022). "The role of mTOR and cross-talk with inflammatory and sympathetic systems and insulin signaling are very new and interesting observations and deserve further study to understand the molecular pathophysiology responsible for the increased cardiovascular disease associated with MetS." (PMID 20809949, 2010). "Investigating the mTOR and AMPK-mTOR pathway mediated autophagy in Drosophila cardiac tissue is crucial for developing therapies for cardiovascular diseases." (PMID 40099194, 2025). "These strategies aim to modulate the intricate cellular mechanisms regulated by mTOR and its modifications, thus offering a refined approach to managing cardiovascular diseases." (PMID 40734978, 2025). "The growing understanding of protein modifications and mTOR signaling in cardiovascular diseases has paved the way for the development of targeted therapies." (PMID 40734978, 2025). "Regulatory mechanisms of protein modifications linking mTOR signaling and cell death in cardiovascular diseases." (PMID 40734978, 2025). "While less regulated than PCD, necrosis is a significant driver of acute tissue injury in cardiovascular diseases, and mTOR plays a role in its regulation." (PMID 40734978, 2025). "Therapeutic compounds targeting mTOR signaling or protein modifications in cardiovascular disease models." (PMID 40734978, 2025). "In the mammalian and human heart, both mTORC1 and mTORC2 complexes of the mTOR signaling pathway play critical roles in cardiac physiology and the pathology of cardiovascular diseases, including cardiac fibrosis and inflammation." (PMID 40099194, 2025). "Ferroptosis, a recently identified form of iron-dependent cell death, is regulated by mTOR in certain cardiovascular diseases." (PMID 40734978, 2025). "Previous studies have demonstrated that AMPK/mTOR signaling not only regulates glucose, lipid, and protein metabolism across the body but also affects blood sugar and lipid levels in cardiovascular disease." (PMID 39980347, 2025). "These disease-specific mechanistic insights emphasize the importance of targeting discrete mTOR-PTM-cell death axes for precision therapy in cardiovascular diseases." (PMID 40734978, 2025). "Increasing evidence has shown that the AMPK/mTOR signaling pathway is involved in cardiovascular diseases." (PMID 39980347, 2025). "The AMPK/mTOR pathway plays a pivotal role in the regulation of autophagy, particularly in cardiovascular diseases." (PMID 39980347, 2025). "The research indicated that the PI3K/Akt/mTOR signaling pathway plays a critical regulatory role in the pathogenesis of both tumors and cardiovascular diseases." (PMID 40196368, 2025). "This table provides a comprehensive overview of the therapeutic landscape targeting protein modifications and mTOR signaling in cardiovascular diseases, emphasizing both established treatments and promising drug candidates." (PMID 40734978, 2025).
cardiovascular diseases (continued). "BCAAs promote the occurrence and development of cardiovascular disease, dependent on TG metabolism via activation of the mTOR." (PMID 41156532, 2025). "Understanding the intricate relationship between mTOR and cell death mechanisms is crucial for developing novel therapeutic strategies targeting mTOR signaling in cardiovascular diseases." (PMID 40734978, 2025). "Since FLCN is part of this mTOR signaling cascade, its influence on cardiac function and cardiovascular diseases will need to be studied further." (PMID 39865126, 2025). "PI3K/Akt/mTOR is a key signaling pathway that regulates autophagy, and then affects the development of cardiovascular diseases." (PMID 38807081, 2024). "Taken toghether, this suggests that Rapalink-1, by inhibiting the activation of NF-κB, MAPKs, and mTOR, can suppress senescence and can thus be beneficial against cardiovascular diseases." (PMID 37998344, 2023). "Small‐molecule modulators based on the manipulation of mTOR have been investigated in a variety of cardiovascular diseases." (PMID 36869852, 2023). "PI3K/Akt/mTOR pathway plays an important role in the occurrence, development and treatment of cardiovascular diseases by regulating autophagy." (PMID 37063954, 2023). "Due to the bidirectional role of autophagy in cardiovascular diseases, the importance of balancing autophagic activity of PI3K/Akt/mTOR pathway in the treatment of cardiovascular diseases becomes very important." (PMID 37063954, 2023). "More and more literature have shown that AMPK/ mTOR signaling pathway is participated in the process of cardiovascular diseases." (PMID 37063954, 2023). "Lately, evidence has revealed that Ras/Raf/MEK/ERK pathway via regulation of autophagy by mediating mTOR plays an important role in cardiovascular diseases." (PMID 37063954, 2023). "In conclusion, it is necessary to further emphasize the bidirectional role of AMPK/mTOR pathway in cardiovascular diseases." (PMID 37063954, 2023). "PI3K/Akt/mTOR pathway is activated highly in cardiovascular diseases, and inhibition of mTOR plays a protective role in myocardial cell damage." (PMID 37063954, 2023). "The AKT/mTOR pathway is a classical intracellular signaling pathway, and its abnormal activation or dysfunction can affect the pathological processes of various cardiovascular diseases." (PMID 37990246, 2023). "The mammalian target of rapamycin (mTOR) is involved in the regulation of various cellular functions and is closely related to the development of cardiovascular diseases (CVDs)." (PMID 36438564, 2022). "Then, we highlight the targets (SIRT1 and mTOR) that regulating cellular senescence in cardiovascular disorders." (PMID 35111365, 2022). "In conclusion, mTOR inhibitors have a high potential to modulate inflammation in cardiovascular disorders by breaking the vicious cycle of autonomously maintained inflammation and boosting tolerance mechanisms." (PMID 35845058, 2022). "Overall, this review will focus on the advancements, prospects, and limits of regulating mTOR signaling in cardiovascular disease." (PMID 35845058, 2022). "MTOR is targeted by perhexiline, a drug used for cardiovascular disease that inhibits the serine/threonine-protein kinase mTOR." (PMID 36450729, 2022). "Recent research shows that mammalian target of rapamycin (mTOR) signaling plays an important role in the general and inflammation-driven mechanisms that underpin cardiovascular disease." (PMID 35845058, 2022). "A large number of studies have suggested that the AMPK/mTOR/P70S6K pathway plays an important role in cardiovascular disease by strengthening autophagy and that suppression of the mTOR/P70S6K pathway through AMPK activation can enhance autophagic flux." (PMID 35432800, 2021). "As the KEGG enrichment, the top identified pathway was PI3K-Akt signaling pathway and another notable pathway was the mTOR signaling pathway (q value < 0.05), which were involved in cardiovascular disease." (PMID 32733962, 2020).
cardiovascular diseases (continued). "The relationship between leptin and mTOR signaling, and its implication in pathophysiological conditions such as cardiovascular diseases, has been previously discussed and reviewed in the literature." (PMID 33316969, 2020). "Existing studies have indicated that mTOR can affect various biological processes, including cardiomyocyte proliferation, cardiac remodeling, and energy metabolism, in patients with cardiovascular diseases." (PMID 32940379, 2020). "Mammalian target of Rapamycin (mTOR) was shown to have an important role in cardiovascular diseases, oxidative stress and longevity." (PMID 31013989, 2019). "The potential effect of the inhibition of the mTOR pathway in the treatment of cardiovascular diseases warrants further investigation." (PMID 30223891, 2018). "Most remarkably, changes in epigenetic signature of miRs upon mTOR inhibition can lead to identify novel miRNA-based treatment for cardiovascular diseases." (PMID 30305865, 2018). "The mammalian target of rapamycin (mTOR) is a serine/threonine kinase and its role in regulating autophagy, oxidative stress and cardiovascular disease has received intense attention." (PMID 29314656, 2018). "We have also highlighted the latest advances on mTOR-targeted therapy in clinical trials and the new perspective therapeutic strategies with mTOR-targeting miRs in cardiovascular diseases." (PMID 30305865, 2018). "However, disruption of the phosphoinositide 3-kinase (PI3K)-protein kinase B (Akt)-mammalian target of rapamycin (mTOR) signaling pathway has been linked to cardiovascular disease; thus, investigating the effects of FZ extracts on this pathway may clarify the mechanism of cardiotoxicity." (PMID 30405071, 2018). "Down regulation of mTOR signaling by rapamycin has been shown to reduce the development of cardiovascular diseases such as cardiac hypertrophy." (PMID 28400571, 2017). "mTOR has been extensively studied in tumors, cardiovascular diseases, and neurodegenerative disorders." (PMID 26770837, 2015). "Akt/mTOR signaling is involved in ischemic cardiomyocyte and apoptosis cardiovascular disease." (PMID 40003867, 2025). "In cardiovascular diseases, the cross-talk between ubiquitination and SUMOylation may regulate mTOR's stability and activity, controlling the growth and death of cells such as cardiomyocytes, endothelial cells, and smooth muscle cells." (PMID 40734978, 2025). "Notably, several ongoing clinical trials support the translational relevance of targeting mTOR or PTM pathways in cardiovascular diseases." (PMID 40734978, 2025). "In particular, the mTOR signaling pathway, a central regulator of autophagy, plays a pivotal role in linking chronic stress and mitochondrial dysfunction to autophagic imbalance in cardiovascular diseases." (PMID 40099194, 2025). "Additionally, the PI3K/Akt/mTOR pathway plays a crucial role in the treatment of cardiovascular diseases, highlighting its dual significance in both oncology and cardiology." (PMID 40196368, 2025). "mTOR is a serine/threonine-specific protein kinase that contained two different multi-complexes, where mTORC1 is critical in many physiological processes, including cardiovascular diseases." (PMID 38308007, 2024). "At the transcriptome level, the aging HGPS VSMCs demonstrated marked upregulation of pathways associated with cardiovascular disease including extracellular matrix remodeling, MAPK and mTOR signaling, as did control iPSC‐derived VSMCs, although at a diminished level." (PMID 38576084, 2024). "These evidences suggest that p62 may play the role of cardiovascular diseases promoter by regulating many signaling pathways, including mTOR and autophagy." (PMID 37063954, 2023). "Hence, in view of the controversial situation of PI3K/Akt/mTOR in cardiovascular diseases, we can carefully consider the different period of cardiovascular diseases and the control of autophagic activity." (PMID 37063954, 2023).
cardiovascular diseases (continued). "In the later period of cardiovascular diseases, excessive activation of autophagy via inhibition of PI3K/Akt/mTOR pathway may cause autophagic cell death, so as to exacerbate the development of cardiovascular diseases." (PMID 37063954, 2023). "These evidences suggest that activation or inhibition of PI3K/Akt/mTOR pathway may be beneficial to the treatment of cardiovascular diseases." (PMID 37063954, 2023). "Pro-inflammatory mediators and their signaling cascades, such as NF-B, Hippo, and mTOR, cooperate in the interaction between inflammation and cardiovascular disease to regulate cell fate plasticity and mold different biological activities in cardiomyocytes and immune cells." (PMID 37626701, 2023). "We tested the activity of the AMPK/mTOR signalling pathway, which is a potential target pathway of resistin in cardiovascular diseases, to further determine the molecular mechanism of H. parasuis-induced resistin in regulating claudin-5 and occludin expressions in PAECs." (PMID 36694280, 2023). "PI3K/AKT/mTOR signalling contributes to several cardiovascular disorders." (PMID 36869852, 2023). "This suggests that DDiT4L may be a therapeutic target in cardiovascular diseases when autophagy and mTOR signaling pathways play important roles." (PMID 38089628, 2023). "Moreover, we highlight the role of SIRT1 and mTOR in regulating senescence during age-related cardiovascular diseases." (PMID 35111365, 2022). "Although the mechanisms remain unclear, mTOR activation-related autophagy depression is involved in senescence and cardiovascular diseases." (PMID 35111365, 2022). "Moreover, the involvements of subsequent PI3K/AKT/mTOR signaling pathway and Wnt signaling pathway in endothelial function and in the pathobiology of cardiovascular diseases are proposed." (PMID 32733962, 2020). "Moreover, mTOR and ROS signaling pathways are reported in the molecular basis of aging-related diseases especially cardiovascular diseases." (PMID 32235006, 2020). "Nevertheless, conceptual treatments in laboratory models describing mTOR inhibition mediated miR changes and vice versa are encouraging and may lead to novel treatments in cardiovascular diseases in the future." (PMID 30305865, 2018). "Further studies examining the association between regulatory pathway of autophagy and cardioprotective effects of mTOR activators may provide novel therapeutic strategies for cardiovascular disease management." (PMID 27385290, 2016). "mTOR plays a significant role in the development of cardiovascular disease." (PMID 23326427, 2013). "Metabolic cardiovascular disease is closely regulated through the mTOR signaling pathways." (PMID 22545721, 2012). "Cardiovascular disease also may be mediated through hyperleptinemia and the activation of mTOR." (PMID 22545721, 2012). "Further exploration of autophagy mechanisms in cardiac tissues, particularly through the modulation of mTOR and AMPK pathways in Drosophila, provides valuable insights into developing therapeutic strategies for cardiovascular diseases." (PMID 40099194, 2025). "Despite the promising advances in targeting mTOR signaling and PTM pathways for cardiovascular disease treatment, several translational hurdles remain." (PMID 40734978, 2025). "The NLRP3 inflammasome has been identified as an important biomarker in many cardiovascular diseases, including AF, with the crosstalk between the PI3K/AKT/mTOR pathway and the NLRP3 inflammasome potentially influencing the autophagy response in AF." (PMID 40498015, 2025).
cardiovascular diseases (continued). "Therefore, Sesn2 can activate downstream AMPK and inhibit mTOR signal to induce autophagy, so as to regulate the occurrence and development of cardiovascular diseases, suggesting that Sesn2 may be a pharmacological target for treating cardiovascular diseases." (PMID 37063954, 2023). "Previously, Sestrin2 is considered to be cardioprotective in several models of cardiovascular diseases, including myocardial infarction and cardiac dysfunction induced by ER stress or lipopolysaccharide, via AMPK/mTOR signaling cascade." (PMID 37920252, 2023). "Accumulating evidence suggests that PTEN plays a critical role in cardiovascular disease by inhibiting AKT-dependent pathways (GSK3, FOXO, and mTOR) and PINK1-AMPK signaling cascades." (PMID 33251220, 2020). "In summary, mTOR plays a dual role in both programmed and non-programmed cell death in cardiovascular diseases." (PMID 40734978, 2025). "Pik3r5 encodes the catalytic subunits of PI3K signaling pathway which could control AKT/NO/mTOR, NADPH oxidase, and TGF-b/Smad pathway that are involved in cardiovascular diseases." (PMID 37071017, 2023). "In our study, kidney transplant recipients had the highest proportion of cardiovascular diseases, and lung transplant recipients more commonly received CNI/mTOR inhibitors and corticosteroids, which could partly explain the differences in the immune response." (PMID 36713395, 2022). "Our results demonstrated that BP protected HUVECs against oxidative damage partly via PI3K/Akt/mTOR-mediated Nrf/HO-1 pathway, which might be applied into preventing Ox-LDL mediated cardiovascular diseases." (PMID 31360208, 2019). "Unlike canonical drug-eluting stents that target mTOR or other pathways, PCK1 might be considered a potential target for cardiovascular diseases associated with vascular restenosis on the basis of its unique regulation of the STAT3/DRP1 pathway." (PMID 39262325, 2024).